PGR (progesterone receptor)
Diseases named in the same sentence as PGR in open-access papers (continued):
Sharing a sentence is not in itself a finding about the gene and the disease.
cancer (continued). "On the other hand, Bcl-2 expression was found to correlate with that of ERα and PgR, i.e. with differentiated cancer phenotypes." (PMID 27538498, 2016). "PgR, an oestrogen-regulated gene, requires oestrogen and ER for its synthesis in normal and cancer cells." (PMID 25938238, 2015). "Progesterone receptor (PR) positive cancers showed mem-PankoMab-GEXTM staining more often than those being PR negative (p = 0.028)." (PMID 25986064, 2015). "Mifepristone is a progesterone receptor antagonist that has been widely used as the abortifacient and in anti-cancer trials." (PMID 26459390, 2015). "The current ASCO/CAP defines HR expression as the presence of at least 1% of invasive cancer cells staining for either ER or PgR." (PMID 26161666, 2015). "Breast cancer is generally classified based on the receptors overexpressed on the cancer cell membrane, such as estrogen receptor (ER), progesterone receptor (PR) and human epidermal growth factor receptor 2 (HER2)." (PMID 26313651, 2015). "The PABC group had larger tumors, more advanced cancer stage, and tumors with less progesterone receptor than the comparison group." (PMID 25415309, 2014). "In the present study, basal-like cancer was defined as ER−, PgR−, HER2−, CK 5/6+ and/or EGFR+ tumors using immunohistochemical surrogate markers." (PMID 24932232, 2014). "Other factors associated with lower odds were older age, later year of diagnosis, having ≥2 conditions detected prior to cancer, being either estrogen and/or progesterone receptor positive, and living in a census tract with >12% poverty." (PMID 24688795, 2014). "4EBP1 protein was confirmed as an independent prognostic factor, especially in progesterone receptor (PgR)-expressing cancers." (PMID 24131622, 2013). "In this study, two cancer cell lines that exhibited over a 30-fold difference in progesterone receptor (PR) transcription rates were each transfected with siRNA targeting the PR promoter." (PMID 24832229, 2012). "Follow up should encompass early detection of new cancers as well as recurrence and maximise adherence to preventive endocrine therapy in those patients with oestrogen or progesterone receptor positive cancers." (PMID 22695275, 2012). "Breast cancer differ, for example, with respect to oestrogen (ER) and progesterone receptor (PR) status; hormone receptor-positive cancers exhibiting better differentiated morphological appearance and stronger clinical response to hormonal treatment." (PMID 21157446, 2011). "Increased time from diagnosis of cancer to diagnosis of bone metastases and positive progesterone-receptor status significantly correlated with increased survival (p ≤ 0.011)." (PMID 19660124, 2009). "Both ER isoforms as well as the progesterone receptor (PR) were detectable in cancer cells of the oral cavity, the salivary gland, and in laryngeal/hypopharyngeal cancers, whereas the tumor stroma was mostly negative." (PMID 19794826, 2009). "This can be explained at least partially by correlation of vimentin expression with ER and PgR negativity, and with higher grade of cancer." (PMID 19695088, 2009). "An interesting finding was that most hereditary cancers (75% of the whole group) were triple-negative: ERα(-)/PgR(-)/HER-2(-) but almost half of this group (44.4%) showed the expression of ERβ." (PMID 18405391, 2008). "An interesting finding of this study is that most hereditary cancers have been found to be triple-negative: ERα(-)/PgR(-)/HER-2(-)." (PMID 18405391, 2008). "According to the immunohistochemical analysis the cancer cells were estrogen and progesterone receptor positive." (PMID 18950495, 2008). "Women with PgR-positive and PgR-negative cancer appeared to benefit equally from letrozole compared with tamoxifen." (PMID 17892469, 2007).
cancer (continued). "Expression of many ERα target genes, including GREB1 (gene regulated in breast cancer 1), PGR (the progesterone receptor gene) and PRLR (the prolactin receptor gene), was induced by oestradiol and blocked by fulvestrant, but only in cells transduced with ERα." (PMID 17573968, 2007). "Tamoxifen significantly reduced monoclonal antibody Ki-67 (MIB-1), estrogen receptor (1D5) and progesterone receptor positivity (PgR 636) in the breast epithelium of carcinoma patients treated with a 10 mg dose of tamoxifen for 14 days." (PMID 16972993, 2006). "Within the ERα-negative group, there was a positive correlation between the degree of staining for AGR2 (>1% carcinoma cells stained) and the degree of staining for PgR (n=47 cases; Spearman's correlation coefficient 0.48; P=0.0007)." (PMID 16598187, 2006). "In comparison with BRCA1 or BRCA2 cancers, familial non-BRCA1/2 cancers represented a much greater number of ER-positive and PgR-positive cases; however, in comparison with the unselected control group they were more receptor-negative." (PMID 15642173, 2005). "Carcinomas in the under 30 years age group had a lower incidence of oestrogen and progesterone receptor positivity." (PMID 8956795, 1996). "The HR-positive cancers, characterized by the expression of progesterone receptor (PR) and/or estrogen receptor (ER), may be responsive to hormone therapy." (PMID 41234386, 2025). "Furthermore, estrogen receptor (ER) and progesterone receptor (PR) are frequently co-expressed, thus rendering hormone receptor positivity a defining characteristic of this carcinoma." (PMID 39897239, 2025). "The progesterone receptor (PGR), a steroid-responsive nuclear receptor activated by progesterone, plays pivotal roles in normal mammary gland development, pregnancy, brain function, and cancer advancement." (PMID 38424455, 2024). "The regulation of gene expression by NR is crucial for metabolism, cancer, neurological diseases, development, and immune responses, with key target genes, such as those for the GR, AR, PGR, ER, and PPARγ, governing specific pharmacological effects in particular tissues." (PMID 39065726, 2024). "Estrogen receptor (ER)-positive cancers contain cells that respond to estrogen signaling, progesterone receptor (PR)-positive cancers respond to progesterone signaling, and cancer subtypes that respond to neither estrogen nor progesterone are deemed hormone receptor (HR)-negative." (PMID 38672402, 2024). "The downregulated expression of PgR in the tissue of patients diagnosed with EC could suggest grade III cancer." (PMID 38337838, 2024). "Concerning the expression levels of the target genes evaluated in the present study, HYAL1, VEGFα, CD20, and PGR genes presented a similar pattern of response, showing significantly higher levels of expression both in benign and malignant tumours when compared to the control group." (PMID 38256245, 2024). "Cancer stage, estrogen, progesterone receptor, Her2 positivity are featured in S2 Table in S1 File." (PMID 37252927, 2023). "Concomitantly, E2 and P4 monotherapies triggered cell cycle arrest and apoptosis in the SW480 and HT29 cells, and while pre-treatment with ERα-blocker enhanced the effects of E2, ERβ-blocker and PGR-blocker suppressed the E2 and P4 anti-cancer actions, respectively." (PMID 37206439, 2023). "However, in a recent clinical guideline update, 1% is recommended as a cutoff value for ER- and PgR-positive cells because of limited but present data on endocrine therapy benefit for cancers with 1% to 10% of cells staining ER positive." (PMID 36721218, 2023). "From the METABRIC cohort, low CYP2S1 mRNA expression was significantly associated with positive progesterone receptor (PgR) (χ2 = 10.400, df = 1, p = 0.001), HER2‐negative status (χ2 = 11.652, df = 1, p = 0.001), and luminal A cancers (χ2 = 15.377, df = 5, p = 0.009)." (PMID 35902379, 2022).
cancer (continued). "AR positivity is generally higher in luminal cancers (ER/PgR-positive cancers), and it may be reasonable that mucinous cancers with higher ER/PgR positivity have higher AR positivity." (PMID 36553136, 2022). "More specifically, prevailing in women, breast and ovarian malignancies are types of cancer that may be provoked by modifications of ERα, ERβ, progesterone receptor (PR), and HER2." (PMID 35327605, 2022). "Most breast cancers express specific hormone receptors (HRs) for estrogen (estrogen receptor α, ERα) and progesterone (progesterone receptor, PR), and some cancers exhibit human epidermal growth factor receptor 2 (HER2)/erb-b2 receptor tyrosine kinase 2 (ERBB2) gene amplification or overexpression." (PMID 35178385, 2022). "Accordingly, ESR1, ESR2, and PGR may be prognostic biomarkers as well as potential therapeutic targets for a variety of cancer types, necessitating further evaluation." (PMID 34322374, 2021). "A prominent example of cancer biomarkers include the estrogen receptor (ER), the progesterone receptor (PR), and the human epidermal growth factor receptor (HER2), all of which are essential for the standard care of newly diagnosed, recurring, and malignant breast cancer patients." (PMID 35071996, 2021). "Together, ESR1, ESR2, and PGR isoforms are differentially expressed in different cancer types." (PMID 34322374, 2021). "Overall, stronger associations were found for progesterone-receptor–negative and oestrogen-receptor–negative cancer types for vegetable intake, fibre from vegetables, and Mediterranean diet." (PMID 34684583, 2021). "A higher percentage of postmenopausal women (p = 0.0157) as well as a significantly higher percentages of patients with positive estrogen receptor status (p = 0.0225) and progesterone receptor status (p = 0.0014) in cancer cells were also observed more frequently in the BCT group." (PMID 33804935, 2021). "Together, ESR1, ESR2, and PGR are differentially expressed in multiple cancer types." (PMID 34322374, 2021). "A small number of hypoxia-associated genes (APLN, HIF1A, and BNIP3), cancer stem cell (CSC) markers (CD24 and CD44), hormonal regulation (HR) genes (ESR1, PGR, and TFF1), other selected genes (PPARGC1A, ILK), and HKGs (RPL32, GUSB, TBP, OAZ1 and NONO) were also included in the panel." (PMID 34206049, 2021). "Considering these results, we hypothesized that genetic alterations in ESR1, ESR2, and PGR play an essential role in cancer progression and combining the expression levels of ESR1, ESR2, and PGR provide prognostic value." (PMID 34322374, 2021). "In our study, we selected ESR1, ESR2, and PGR for an in-depth analysis of mRNA expression, genetic alternations, and clinical outcomes as well as the co-expression of these genes with immunomodulatory factors in a variety of cancer types." (PMID 34322374, 2021). "However, the roles of ESR1, ESR2, and PGR in other cancer types have rarely been studied and further investigations are needed to reach a consensus." (PMID 34322374, 2021). "Based on the cancer response, BC can be divided into estrogen receptor (ER)-positive (response to estrogen signaling), progesterone receptor (PR)-positive (response to progesterone), ER/PR-positive, and human epidermal growth factor receptor-2 (HER2)-positive tumors." (PMID 33863385, 2021). "Given that absence of PgR expression is also related to cancer progression, it is suggested that plasma S1P is closely associated with progression of cancer." (PMID 34948163, 2021). "ESR1, ESR2, and PGR are potential prognostic markers and therapeutic targets, as well as important factors for the prediction, evaluation, and individualized treatment in several cancer types." (PMID 34322374, 2021). "The estrogen receptor (ER) and the progesterone receptor (PR), similar to other members of the steroid hormone receptor family, are ligand-induced transcription factors that play an important role in the biology of the cancer mammary gland." (PMID 34830472, 2021).
cancer (continued). "Interestingly, the frequency of PgR expression in ERα(+)/ERαΔ7-high basal carcinomas was 29.7% compared to 85.2% for ERα(+)/ERαΔ7-low luminal B carcinomas." (PMID 34638241, 2021). "HR+ cancers express estrogen receptors (ER) and/or progesterone receptors (PgR)." (PMID 32351542, 2020). "The selective progesterone receptor modulator mifepristone (MF) may act as a potent antiproliferative agent in different steroid-dependent cancers due to its strong antagonistic effect on the nuclear progesterone receptor (PGR)." (PMID 33158280, 2020). "Furthermore, 65% of these cancers are also progesterone receptor (PR)-positive and PR expression is used as a biomarker of ER signaling." (PMID 32106399, 2020). "ER(−)/PgR(+) tumors show a profile resembling triple- and double-negative tumors, which may indicate that their biology is similar to basal-like carcinomas." (PMID 32825530, 2020). "Patients with luminal breast cancers that are hormone receptor positive (estrogen receptor (ER+) and progesterone receptor (PR+)), may suffer cancer recurrence, which often metastasize to bone but respond well to endocrine therapies." (PMID 30104711, 2019). "In cancer tissues, PGR expression may be regulated by DNA methylation of the proximal promoter region of PGR." (PMID 30728052, 2019). "However, the proportions of patients who had progesterone receptor- or human epidermal growth factor receptor 2-positive cancer were significantly higher in the BRCA-positive than in the BRCA-negative group." (PMID 31031710, 2019). "Also, mounting evidence demonstrate that estrogen and its target gne progesterone receptor (PR) play critical roles in regulatiing breast cancer progression and cancer stem cell fate." (PMID 30250760, 2018). "Positive KIBRA nuclear expression (KIBRAN) (score 2 or 3) was significantly associated with low recurrence rate (p = 0.014), low lymph node stage (0 or 1) (p = 0.006), positive ER expression (p < 0.001), positive PgR expression (p < 0.001) and Ki67 positivity in ≥14% of cancer cells (p < 0.001)." (PMID 29793439, 2018). "Triple negative breast cancer (TNBC) encompasses a heterogeneous group of cancers, the treatment of which remains a challenge due to the absence of targetable molecules such as estrogen receptor (ER), progesterone receptor (PR), or epidermal growth factor receptor 2 (HER2)." (PMID 30254632, 2018). "Once ER and/or PgR are detected, the specimens are considered estrogen dependent and endocrine therapies including ER antagonists and aromatase inhibitors are introduced for patients with early stage cancers." (PMID 28489882, 2017). "Moreover, mature miRNAs expression negatively correlated with Oestrogen Receptor (ER) expression in cancer cells, but only miR-9-5p expression showed a strong negative correlation with expression of Progesteron Receptor (PgR)." (PMID 28345661, 2017). "ER/PgR‐negative cancer and ErbB2‐positive cancer, defined as ErbB2‐enriched, are associated with more aggressive disease and poor prognosis in the absence of effective treatment." (PMID 28781955, 2017). "In short, if we compare cancers positive for ER and PgR, where HER2 expression increases Ki67 values, with the ER-PgR- cancers, were HER2 expression decreases otherwise very high KI-67 values, these unexpected differences obviously required further examinations." (PMID 28356061, 2017). "Several studies have succeeded in identifying tumor biomarkers for cancer detection, diagnosis or prognosis determination for specific types of cancer, such as estrogen receptor and progesterone receptor in breast cancer and prostate-specific antigen in prostate cancer." (PMID 26812883, 2016). "Thus far, new MRI probes targeted to the progesterone receptor were also synthesized, demonstrating specific enhancement in progesterone – positive cancer cells and animal model tumors." (PMID 27200289, 2016).
cancer (continued). "In-depth analyses of the wetness-heat constitution showed that bitter taste/smelly mouth was an independent risk factor for severe CINV (OR = 1.209, 95 % CI: 1.035–1.412, P = 0.017), as well as progesterone receptor-positive cancer (OR = 1.429, 95 % CI: 1.030–1.981, P = 0.032)." (PMID 27829423, 2016). "It is somehow intriguing that restoration of ERα without changing nuclear progesterone receptor levels renders cancer cells susceptible to megesterol acetate." (PMID 27527851, 2016). "PGR expression showed significant differences when comparing benign mammary tumors (p = 0.005), simple tubular carcinomas (p = 0.003) and carcinomas arising in a benign tumor (p = 0.024) of fresh frozen and FFPE samples with a higher expression in fresh frozen samples." (PMID 27649560, 2016). "ER and PgR expression was conservatively defined as 10% or greater staining of cancer cells." (PMID 26161666, 2015). "Furthermore, detailed analysis of our data found that postmenopausal ER-/PgR- cancer cases and controls who starting smoking at ≤19 years tended to be heavy, long-term smokers (data not shown)." (PMID 24516791, 2014). "Furthermore, the survival time was independent on the expression of estrogen and progesterone receptors (PGR) in the cancer tissues." (PMID 25429284, 2014). "No estrogen receptor (ER) or progesterone receptor (PR) immunoreactivity was detected in their associated malignant tumors, human epidermal growth factor receptor-2 (HER-2) protein weak expression was found by immunohistochemistry." (PMID 25230850, 2014). "As previously reported, P-cadherin expression was significantly associated with high-grade carcinomas (p < 0.0001), HER2-overexpressing and basal-like molecular subtypes (p < 0.0001), ER and PgR negativity (p < 0.0001), high expression of HER2 (p < 0.0001), as well as with high Ki67 (p = 0.0141)." (PMID 25269858, 2014). "The cancer types of the three observed PALB2 mutation positive individuals fitted well to that described previously: all three cases had ductal tumor histology and exhibited positive estrogen and progesterone receptor status." (PMID 23941127, 2013). "A systematic and larger study, taking ER-β status into consideration, for patients with different positivity for receptors (ER-β, ER-α and PgR) could better characterize each cancer and help to optimize adjuvant treatment for BC patients." (PMID 24047421, 2013). "None of the GWAS have identified the +331 G/A PgR polymorphism as a risk factor for cancer predisposition despite this functional SNP has been established." (PMID 23349706, 2013). "Another factor that might interfere with cancer development is the receptor status [estrogen receptor (ER) or progesterone receptor (PR)]." (PMID 24171049, 2013). "Interestingly, all three patients with BC presented ductal form of the cancer and estrogen and progesterone receptor positive status." (PMID 23967248, 2013). "Our approach, additionally, could predict the progesterone receptor statuses of the cancer patients." (PMID 22028780, 2011). "According to recent reports, changes in ER and PgR due to primary and relapse cancers are common." (PMID 22004841, 2011). "BRCA1-associated cancers are typically high-grade and are 'triple negative'; i.e. are negative for estrogen-receptor (ER), progesterone-receptor (PR) and HER2 expression." (PMID 19298662, 2009). "Direct evidence for a phenotype shift, especially in tamoxifen-treated patients may be obtainable by comparing recurrent disease with the primary cancer or monitoring PgR status in peripheral blood as has been done for HER-2." (PMID 16434989, 2006). "Furthermore, there is a very high coverage mammography screening (in the general age group 50–60 years) in Finland, aiding in finding asymptomatic cancers, which are more often ER-positive as well as being of lower grade and PgR-positive." (PMID 15642173, 2005).